ERI3 (ERI1 exoribonuclease family member 3)
Synonyms: PINT1; PRNPIP; FLJ22943
Tractability: Small molecule: a structure with a bound ligand is known. PROTAC: ubiquitination databases record sites on it; its protein half-life has been measured.
Gene: Protein-coding gene on chromosome 1 (44,221,070 to 44,355,267, reverse strand). Ensembl gene ENSG00000117419.
Subcellular location (Human Protein Atlas): Cytosol; Nucleoplasm
Gene Ontology:
Molecular function: RNA binding; 3'-5'-RNA exonuclease activity; nucleic acid binding
Biological process: exonucleolytic trimming to generate mature 3'-end of 5.8S rRNA from tricistronic rRNA transcript (SSU-rRNA, 5.8S rRNA, LSU-rRNA); negative regulation of regulatory ncRNA-mediated heterochromatin formation
Cellular component: cytosol
Genetic constraint (gnomAD): Loss-of-function variants: 17 observed, 39.15 expected, observed/expected ratio (o/e) 0.43, 90% interval 0.3 to 0.65. The upper end of that interval is the gene's LOEUF score, 0.65, which puts it in group 2 of 6, group 1 being the genes least tolerant of losing a copy. Missense variants: 289 observed, 414.41 expected, observed/expected ratio (o/e) 0.7, 90% interval 0.63 to 0.77. Synonymous variants: 180 observed, 159.24 expected, observed/expected ratio (o/e) 1.13, 90% interval 1 to 1.28.
Homologues: Orthologues: chimpanzee ERI3 (100% identical), macaque ERI3 (100% identical), guinea pig ERI3 (99% identical), dog ERI3 (99% identical), mouse Eri3 (98% identical), pig ERI3 (93% identical), rabbit ERI3 (92% identical), rat Eri3 (85% identical), tropical clawed frog eri3 (61% identical), Caenorhabditis elegans R02D3.8 (31% identical), Caenorhabditis elegans M02B7.2 (29% identical). Paralogues in human: ERI1 (27% identical), ERI2 (25% identical).
Diseases named in the same sentence as ERI3 in open-access papers:
ERI3 is named in the same sentence as 5 diseases in open-access papers, as found by Europe PMC text mining. Sharing a sentence is not in itself a finding about the gene and the disease. The quoted sentences say what the papers report.
hepatocellular carcinoma (1 paper, 2021). A malignant tumor that arises from hepatocytes. "Thus far, there have been few studies on BOD1, GDI2, GTF3C6 and ERI3’ impact on hepatocellular carcinomas." (PMID 34760691, 2021).
infection (1 paper, 2016). The state of being infected such as from the introduction of a foreign agent such as serum, vaccine, antigenic substance or organism. "ERI3 knockdown was performed using two independent siRNAs (siERI3_III and siERI3_VII) transfected 48 hours prior to infection." (PMID 27682269, 2016). "ERI3 knockdown was performed using two independent siRNAs (siERI3_III and siERI3_VII) transfected 48 hours prior to infection with DENV-2 (MOI = 1.0)." (PMID 27682269, 2016). "At 18 hours post-infection, ERI3 primarily localized to similar condensed Golgi structures as TGON2, distinct from areas marked by anti-dsRNA." (PMID 27682269, 2016). "At 20 and 24 hours post-infection, however, the condensed Golgi structure appeared to expand or break down and both ERI3 and TGON2 relocated to within close proximity of dsRNA." (PMID 27682269, 2016). "We performed siRNA-mediated knockdown of ERI3 followed by infection with DENV-2." (PMID 27682269, 2016). "In order to test the functional importance of ERI3 for DENV-2 infection, we performed siRNA-mediated knockdown and infection with DENV-2, YFV17D or EV71." (PMID 27682269, 2016). "ERI3 knockdown significantly reduced the accumulation of DENV-2 RNA and infectious virus at 24 hours post-infection and this was consistent with an effect on viral RNA replication." (PMID 27682269, 2016). "The localization of ERI3 to the Golgi and its relocalization to DENV-2 replication sites during infection highlights a previously unappreciated role for the Golgi in viral replication." (PMID 27682269, 2016). "We analyzed the input and pellet using qPCR and determined that immunoprecipitation of FLAG-ERI3 significantly enriched YFV17D RNA (8.63-fold enrichment, P = 0.03) compared to the IgG control, suggesting there is an interaction between ERI3 and YFV17D RNA during infection." (PMID 27682269, 2016). "In order to validate and extend the role for ERI3 suggested by the proteomic screens, we utilized RNA immunoprecipitation and qPCR to test whether ERI3 interacts with DENV-2 RNA during infection." (PMID 27682269, 2016). "We analyzed the input and pellet for viral RNA and determined that immunoprecipitation of FLAG-ERI3 significantly enriched DENV-2 genomic RNA (gRNA, 21.9-fold enrichment, P = 0.02) compared to the IgG control, demonstrating that ERI3 interacts with DENV-2 RNA during infection." (PMID 27682269, 2016). "Our studies suggest that ERI3 function in viral replication is not linked to the host innate immune response, since RT-qPCR analysis showed similar levels of IFN and ISG mRNA expression following infection in control and ERI3 knockdown cells." (PMID 27682269, 2016).
ERI3 also shares sentences with these, for which no sentence is quoted: cancer (1 paper); ischaemic stroke (1); tumour (1).